ZSCAN31 (zinc finger and SCAN domain containing 31)
Description:
May function as a transcription factor. May be involved in the development of multiple embryonic organs.
Synonyms: ZNF310P; ZNF323; ZNF20-Lp
Tractability: PROTAC: UniProt records ubiquitination sites on it.
Gene: Protein-coding gene on chromosome 6 (28,324,693 to 28,356,271, reverse strand). Ensembl gene ENSG00000235109.
Subcellular location: Nucleus
Subcellular location (Human Protein Atlas): Nucleoplasm; Cytosol
Gene Ontology:
Molecular function: sequence-specific double-stranded DNA binding; DNA-binding transcription factor activity, RNA polymerase II-specific; RNA polymerase II cis-regulatory region sequence-specific DNA binding; sequence-specific DNA binding
Biological process: regulation of transcription by RNA polymerase II
Cellular component: nucleus
Genetic constraint (gnomAD): Loss-of-function variants: 14 observed, 23.35 expected, observed/expected ratio (o/e) 0.6, 90% interval 0.4 to 0.94. The upper end of that interval is the gene's LOEUF score, 0.94, which puts it in group 3 of 6, group 1 being the genes least tolerant of losing a copy. Missense variants: 424 observed, 505.29 expected, observed/expected ratio (o/e) 0.84, 90% interval 0.77 to 0.91. Synonymous variants: 168 observed, 179.62 expected, observed/expected ratio (o/e) 0.94, 90% interval 0.82 to 1.06.
Homologues: Orthologues: chimpanzee ZSCAN31 (99% identical), macaque ZSCAN31 (95% identical), pig ZSCAN31 (81% identical), dog ZSCAN31 (77% identical). Paralogues in human: ZSCAN12 (56% identical), ZKSCAN8 (54% identical), ZNF397 (52% identical), ZSCAN23 (49% identical), ZSCAN30 (49% identical), ZNF232 (47% identical), ZKSCAN1 (47% identical), ZSCAN21 (47% identical), ZSCAN26 (46% identical), ZKSCAN3 (45% identical), ZNF394 (45% identical), ZNF263 (44% identical), and 18 more.
Diseases named in the same sentence as ZSCAN31 in open-access papers:
ZSCAN31 is named in the same sentence as 12 diseases in open-access papers, as found by Europe PMC text mining. Sharing a sentence is not in itself a finding about the gene and the disease. The quoted sentences say what the papers report.
schizophrenia (5 papers, 2018 to 2022). A major psychotic disorder characterized by abnormalities in the perception or expression of reality. "SNP in ZSCAN31 (rs7759855) had the strongest association with the phenotypes for schizophrenia in the Japanese population." (PMID 35801084, 2022). "ZSCAN31, also known as ZNF323, is another cis-eQTL associated gene that has been previously identified as significantly associated with schizophrenia, bipolar disorder and psychosis in both a GWAS and an eQTL study using 193 human prefrontal cortex samples." (PMID 30142156, 2018). "There is evidence that ZSCAN31 is associated with schizophrenia." (PMID 35801084, 2022). "Methylation in promoter regions of ZSCAN31 in the brain had an effect on schizophrenia." (PMID 35801084, 2022).
depression (1 paper, 2023). "Notably, TCF4, NKAPL, ZKSCAN3, ZSCAN16, ZSCAN31 have been associated with depression in previous GWASs." (PMID 36750733, 2023).
hepatocellular carcinoma (1 paper, 2023). A malignant tumor that arises from hepatocytes. "ZSCAN31 is related to PDZ-binding motif (TAZ) expression in hepatocellular carcinoma cells, and the targeting of ZSCAN31 and TAZ could express a novel therapeutic approach in hepatocellular carcinoma cells." (PMID 37426090, 2023).
lung carcinoma (1 paper, 2022). "Among the top 15 FC-specific hypermethylated genes, the methylation of ZSCAN31, KCNA3 and CDO1 were reported to be associated with lung cancer development." (PMID 35313869, 2022). "ZSCAN31 has also been reported to be significantly hypermethylated in lung cancer." (PMID 35313869, 2022).
Tourette syndrome (1 paper, 2023). A neurologic disorder caused by defective metabolism of the neurotransmitters in the brain. "Evidence found that ZSCAN31 might underlie several neurodevelopmental disorders, including ADHD, ASD, Tourette syndrome, and SCZ." (PMID 37658396, 2023).
ZSCAN31 also shares sentences with these, for which no sentence is quoted: bipolar disorder (1 paper); cancer (1); COVID-19 (1); gout (1); neurodevelopmental disorder (1); psychiatric disorder (1); psychosis (1).